CCN6 (cellular communication network factor 6)
Diseases named in the same sentence as CCN6 in open-access papers (continued):
Sharing a sentence is not in itself a finding about the gene and the disease.
cancer (19 papers, 2012 to 2025). A tumor composed of atypical neoplastic, often pleomorphic cells that invade other tissues. "The important role for the TSP1 domain in mediating CCN6 functions in breast tumorigenesis underscores our previous study demonstrating that human metaplastic carcinomas carry a frame shift mutation within the TSP1 domain sequence of CCN6." (PMID 26933820, 2016). "Notably, altered CCN6 expression has also been observed in other cancers, such as colon and pancreatic cancer, where either loss or overexpression contributes to tumorigenesis, underscoring that its effects vary depending on cell type and expression level." (PMID 41009407, 2025). "While CCN6 dysregulation in cancers occurs alongside other contributing factors, PPD is directly attributable to variants in CCN6." (PMID 41009407, 2025). "Comparison of CCN6 mRNA levels among diverse cancer types and adjacent normal tissue revealed that CCN6 expression was significantly downregulated in four types of cancer (KICH, KIRC, SKCM, and TGCT) and significantly upregulated only in OV." (PMID 33833779, 2021). "The studies showed expression and functional roles of CCN6 are also inconsistent among different types of cancer." (PMID 33833779, 2021). "These bioinformatics analyses further suggest that the expression and functions of CCN6 are inconsistent across cancer types." (PMID 33833779, 2021). "The mechanism by which CCN6 regulates epithelial and mesenchymal transitions appears to differ in normal cells and in cancer cells." (PMID 26933820, 2016). "Several matricellular proteins, such as SPARC, OPN, CCN1, CCN6, and TNC, have been implicated in either the promotion or suppression of EMT, highlighting their role in cancer progression and malignant behavior of cancer cells." (PMID 22481923, 2012). "Interestingly, replenished CCN6 markedly reduced the migration of OTUB1−/− 4T1 cells, indicating that OTUB1 influences cancer cell migration by regulating CCN6." (PMID 37608493, 2023). "CCN6 mRNA levels and prognostic value also vary depending on the type of cancer." (PMID 33833779, 2021). "Therefore, MMP-9 may act as the CCN6-responsive mediator, causing ECM degradation, which may lead to subsequent cancer migration and invasion activity." (PMID 30237403, 2018). "Moreover, we examined the effect of CCN6 knocked-down in HSC-2 cells on spheroid formation, which mimics the in vivo behavior of cancer cells." (PMID 37590989, 2023).
skeletal dysplasia (4 papers, 2019 to 2025). Any Mendelian diseases that affects growth and development of the skeleton. "In the present study, four novel mutations in the CCN6 were revealed by WES and confirmed by Sanger sequencing in four multiplex pedigrees displaying similar uncharacterized skeletal dysplasia." (PMID 32351055, 2020).
genetic disease (3 papers, 2012 to 2021). "Biallelic mutations in the CCN6 gene are known to cause a rare genetic disorder-progressive pseudorheumatoid dysplasia (PPD)." (PMID 34650595, 2021).
CCN6 also shares sentences with these, for which no sentence is quoted: lung carcinoma (4 papers); colorectal carcinoma (3); skeletal disease (3); spondyloepiphyseal dysplasia (3); hepatocellular carcinoma (2); juvenile idiopathic arthritis (2); musculoskeletal disorder (2); non-small cell lung carcinoma (2); osteosarcoma (2); polyarticular JIA (2); rheumatoid arthritis (2); albinism (1); Arthritis (1); benign tumours (1); bipolar disorder (1); bone cancer (1); breast (1); carcinosarcoma (1); cartilage disorder (1); cholangiocarcinoma (1); ciliopathies (1); colon cancer (1); congenital adrenal hyperplasia (1); dementia (1); dysplasia (1); epidermoid carcinoma (1); fatty liver disease (1); Gaucher disease (1); hematologic malignancies (1); Hepatic steatosis (1).
A further 19 diseases each share a sentence with CCN6 in 1 paper.